MTOR (mechanistic target of rapamycin kinase)
Diseases named in the same sentence as MTOR in open-access papers (continued):
Sharing a sentence is not in itself a finding about the gene and the disease.
cancer (continued). "Suppression of these mTOR-mediated survival signals provides the opportunity to reactivate default apoptotic pathways in cancer cells and allow them to proceed on the path of death." (PMID 17996122, 2007). "Rapamycin-based therapies target mTOR and are in clinical trials for various cancers including breast." (PMID 17726467, 2007). "Deregulated PKB/Akt activity is common in many cancers and results in mTOR mediated stimulation of G1- S phase progression." (PMID 17407548, 2007). "PI3K/Akt/mTOR signal pathway plays an important role in the course of initiation and progression of carcinoma." (PMID 17996122, 2007). "Inhibition of mTOR-mediated cap-dependent translation, through the use of rapamycin is insufficient to elicit a complete inhibition of cancer cell proliferation." (PMID 16404421, 2006). "Since experimental models implicate translation initiation directly in cancer cell growth, it would be of interest to develop molecules that specifically target downstream components of the mTOR signaling pathways, which control eIF4F formation." (PMID 16404421, 2006). "The serine/threonine kinase, mTOR (mammalian Target of Rapamycin) has become a focus for cancer drug development." (PMID 16953237, 2006). "The basic structure of the pathway was reviewed in this article, together with results of the clinical studies targeting mTOR for cancer therapy." (PMID 15365568, 2004). "Targeting the PAK1/mTOR/p70 S6K pathway could lead to novel treatments that inhibit cancer growth and metastasis, ultimately improving patient outcomes." (PMID 41459112, 2026). "This context-dependent requirement for mTOR is particularly striking, given that rapamycin is widely exploited in cancer research as a potential therapeutic molecule, yet here, its blockade prevents the restoration of protein synthesis and synaptic plasticity in the presence of APOE4." (PMID 41219002, 2026). "Furthermore, transcriptomic profiling and molecular analysis identified LIE as a principal effector, driving extensive transcriptional reprogramming and targeting the MAPK and mTOR pathways as core regulators of its anti-cancer efficacy." (PMID 41900047, 2026). "Treatment with this novel triple PIM/PI3K/mTOR inhibitor may also chemosensitize PDAC to other cancer therapies, such as RAS inhibitors." (PMID 41756246, 2026). "The role of TSC2 and the mTOR signaling pathway in cancer progression is well-established in humans, and the high frequency of these mutations in chimpanzee samples may indicate a parallel, yet distinct, evolutionary adaptation in this species." (PMID 41522204, 2026). "Mechanistically, VANGL1 integrated Wnt/Notch/mTOR signaling with cancer stemness and angiogenesis." (PMID 42294338, 2026). "CBD may modulate treatment responsiveness in cancer by alteringthe PI3K/AKT/mTOR and ERK signaling pathways." (PMID 41288593, 2026). "DeltaTag labels PDEδ at its p.E88 under biologically relevant conditions, modulates mammalian target of rapamycin (mTOR) signalling by disrupting the PDEδ-Rheb (Ras homologue enriched in brain)-mTORC1 (mTOR complex 1) axis and inhibits cancer cell proliferation." (PMID 41617704, 2026). "Integrating PI3 K/AKT/mTOR inhibitors with drugs that target alternative cancer stem cell–related pathways, epithelial–mesenchymal transition regulators, or the tumor microenvironment may enhance treatment effectiveness." (PMID 40676293, 2025). "Functional enrichment analysis further supported the oncogenic role of NOTCH2, revealing significant associations between its high expression and hallmark signaling pathways implicated in cancer progression, including the PI3K-AKT, TGF-β, MAPK, mTOR, and KEAP1-NFE2L2 signaling." (PMID 41200204, 2025). "The data further suggested an under‐activation in the EGFR and JAK–STAT signaling pathways, which might indicate a predominantly PI3K/mTOR‐driven cancer phenotype for this patient, further supporting the rationale for mTOR inhibition." (PMID 39876058, 2025).
cancer (continued). "KEGG pathway enrichment analysis of DEGs comparing high- and low-VGF expression groups in the TCGA-PRAD cohort demonstrated significant involvement of key oncogenic pathways, particularly the mTOR signaling pathway and the PD-L1 expression/PD-1 checkpoint pathway in cancer." (PMID 40592939, 2025). "Additionally, adiponectin downregulates PI3K/AKT and mTOR signaling, which are critical for cancer cell survival and metabolism." (PMID 40387523, 2025). "CMTM4 regulates RTK function and further controls downstream signal activation, including NF-κB and Akt/mTOR pathways, which may induce tumor productions of various cytokines and chemokines in cancer cells, including CCL-1, IL-1β, G-CSF." (PMID 39948411, 2025). "mTOR is frequently deregulated in many cancers, making it a critical target for cancer therapies." (PMID 40855114, 2025). "Therefore, a mechanistic understanding of the regulation of apoptosis and autophagy by the PI3K/AKT/mTOR axis can accelerate the development of cancer treatments." (PMID 40740483, 2025). "Therefore, mTOR activation happens in cancer cells that become resistant to anticancer drugs after long-term treatment." (PMID 40848971, 2025). "Together, these findings highlight the multifaceted relationship between PPARγ activity and mTOR signaling, suggesting that modulation of this axis could have both therapeutic potential and context-dependent metabolic consequences in cancer cachexia." (PMID 41476922, 2025). "In general, the translational machinery is considered to be a valuable therapeutic target for different cancer entities and can be addressed by the translation elongation inhibitor omacetaxine or mTOR inhibitors, respectively, which are currently tested in numerous clinical cancer studies." (PMID 40918647, 2025). "The mTOR protein level is higher in the proposed 3D model compared to the actual tumor tissue most probably because just cancer cells and fibroblasts compose the 3D system while the actual tumor tissue includes many other cell type and matrix where mTOR is not present." (PMID 41220928, 2025). "mTOR plays a pivotal role in cancer growth control upon amino acid response." (PMID 39875724, 2025). "mTOR, the mammalian target of rapamycin, has emerged as a potential target for drug development, particularly due to the fact that it plays such a crucial role in cancer biology." (PMID 40566531, 2025). "The interferon response gene RSAD2, upregulated mechanistically by the JAK/STAT interferon response and PI3K/AKT/mTOR pathways, is a key factor for metabolic reprogramming to enhance lipogenesis and glycolysis, thereby promoting stem-like properties of cancer stem cells and tumor proliferation." (PMID 41439936, 2025). "Inhibition of PI3K/mTOR together will reduce the cancer cell proliferation and induce apoptosis." (PMID 38584538, 2025). "However, the STAT3, nuclear factor-κB (NF-κB), and phosphoinositide 3-kinase/AKT/mammalian target of rapamycin (PI3K/AKT/mTOR) pathways also regulate stemness properties in many cancers." (PMID 40142941, 2025). "Additionally, cancer‐promoting pathways such as mTOR signaling and TGF‐β signaling, were also activated in this group." (PMID 40926349, 2025). "Another clinical trial investigated the role of the HIV protease inhibitor nelfinavir in combination with the current standards of care, temozolomide (TMZ) and radiotherapy, based on data that nelfinavir prevents the growth of cancer cell lines by inhibiting the PI3K/Akt/mTOR pathway." (PMID 40563634, 2025). "These pathways included vitamin B6 metabolism, transcriptional mis-regulation in cancer, pyruvate metabolism, protein digestion and absorption, the mTOR (mammalian target of rapamycin) signaling pathway, the MAPK (mitogen-activated protein kinase) signaling pathway, and ECM-receptor interaction." (PMID 40362379, 2025).
cancer (continued). "The PI3K/AKT/mTOR signaling pathway is commonly dysregulated in cancers and plays a significant role in radioresistance, though its exact mechanisms remain unclear." (PMID 40725100, 2025). "On the contrary, pharmacological inhibition of the PI3K/AKT/mTOR pathway may result in the upregulation of Cyclin D1 or other cell cycle regulatory proteins, effectively enabling cancer cells to circumvent the intended therapeutic effects." (PMID 41348684, 2025). "By inhibiting mTOR, L-asparaginase enhances autophagy in cancer cells, which may serve as a cytoprotective mechanism in some cancers." (PMID 41459545, 2025). "We identified two pro-proliferative genes whose protein expression increased upon BCL2 inhibition, FGFR3 (log2ratio = 0.87, p-value = 2.00E-03) and MTOR (log2ratio = 0.53, p-value = 3.49E-02), which have well-known roles in cancer signaling, i.e., FGFR signaling, and mTOR signaling." (PMID 40568132, 2025). "Notably, THADA overexpression increases cancer growth and malignancy via augmenting the mechanistic target of rapamycin (mTOR) pathway or upregulating PD-L136–38." (PMID 40483304, 2025). "Abundant evidence exists on the involvement of two tightly interconnected MAPK/ERK and PI3K/Akt/mTOR signaling pathways in regulating various hallmarks of cancer cells, like proliferation, stress response, invasion, metastasis, and EMT in different tumor types, including HNSCC." (PMID 40563540, 2025). "Therefore, the PI3K/AKT/mTOR pathway is involved in EMT-related pathways in cancer cells, controlling cytoskeletal reorganization, enhanced cellular motility, and tumor aggressiveness which are hallmarks of metastatic competence." (PMID 40075635, 2025). "In a few cancers, mTOR is also inhibited through ubiquitin modification." (PMID 39759114, 2025). "Therefore, regulating the PI3K/AKT/mTOR pathway to induce toxic autophagy can accelerate apoptosis and ferroptosis in cancers." (PMID 40740483, 2025). "By combining autophagy inhibitors with PI3K/mTOR inhibitors, researchers have observed enhanced tumor cell apoptosis, indicating a synergistic effect that could overcome resistance mechanisms in cancer cells." (PMID 41190025, 2025). "Additionally, OA induced cancer cell apoptosis by suppressing the mTOR signaling pathway and triggered autophagy in an AMPK-dependent manner in vitro." (PMID 40621912, 2025). "Studying the modulation of the mTOR signaling system in vivo by inducing autophagy with bioactive chemicals and monitoring mTOR activity could be a focus of future cancer treatment research." (PMID 40717210, 2025). "In addition, MELK has been shown in multiple cancers to activate PI3K–Akt–mTOR signaling, and these mitogenic pathways can indirectly promote YAP/TAZ activity." (PMID 41278210, 2025). "We observed that the mTOR pathway, known to be induced in the neighbouring surviving cells around dying cancer cells via a paracrine mechanism in unfavorable conditions, also induced HTR2B expression, providing a link between a nutrient-deprived environment and the higher HTR2B level." (PMID 41034989, 2025). "Thus, nanoparticle-mediated drug delivery systems offer a viable approach for targeting the PI3K/AKT/mTOR signaling pathway in cancer treatment." (PMID 40076496, 2025). "PI3K and Akt, upstream factors of mTOR, are suitable therapeutic targets for various cancers." (PMID 41392241, 2025). "Therefore, nanoparticle-based treatments possess considerable promise for targeting PI3K/AKT/mTOR-mediated autophagy in cancer therapy." (PMID 40076496, 2025). "Thus, PI3K/AKT/mTOR pathway is still the most widely promising target for potential anti-cancer therapies." (PMID 41180483, 2025).
cancer (continued). "The aberrant PI3 K/AKT/mTOR pathway is known to be involved in cancer." (PMID 40676293, 2025). "Additionally, the cancer proliferation pathway PI3K/mTOR was inhibited in response to Prohep treatment." (PMID 40405038, 2025). "Therefore, both upregulation and downregulation of the PI3K/AKT/mTOR pathway can be observed in the context of autophagy regulation in cancer therapy." (PMID 40740483, 2025). "In many cancers, mTOR inhibitors have been considered as potential therapeutic drugs, but the activation of mTOR signaling by BCAAs may lead to drug resistance." (PMID 40438606, 2025). "Furthermore, the findings reveal that MYB overexpression counteracts the tumor-suppressive effects of miRNA-195-5p and activates the PI3K/AKT/mTOR signaling pathway, which promotes cancer progression." (PMID 41141380, 2025). "Additionally, mTOR also regulates the programmed death ligand 1 (PD-L1) expression, which allows for cancer cells to evade or inhibit the immune system." (PMID 40407951, 2025). "We assessed the cell proliferation activity using the Ki-67 proliferative activity index and the consumption of the most important amino acids that trigger the mammalian target of rapamycin (mTOR) pathway, which stimulates the consumption of amino acids by cancer cells for their division and growth." (PMID 40429927, 2025). "Translational rewiring downstream of oncogenic signaling (e.g., RAS/RAF/MEK/ERK, PI3K/AKT/mTOR, Wnt/β-catenin) is a key adaptive mechanism in cancer cells that allows specific changes in the proteome to support tumor development, metastasis, and treatment resistance." (PMID 39869680, 2025). "The PI3K/Akt/mTOR signaling pathway is frequently dysregulated in various types of cancers." (PMID 40798865, 2025). "It has been reported that metformin may inhibit the proliferation, invasion, and migration of cancer cells by regulating the AMPK/mTOR pathway." (PMID 39944825, 2025). "Berberine's potential therapeutic benefits against various conditions such as cancer, diabetes, and cardiovascular diseases may be influenced by its ability to modulate the mTOR pathway." (PMID 40717210, 2025). "Hyperactivation of the PI3K/AKT/mTOR pathway promotes tumor progression in many cancers." (PMID 41262902, 2025). "In addition, the amounts of Akt phosphorylation, mTOR, and c‐Myc in cancer cells were reduced after theaflavin treatment, which are typically overexpressed in normal cancer cells." (PMID 40755495, 2025). "From these findings, we speculate that ARL6IP5 may regulate cancers via PI3K-Akt-mTOR signaling pathway." (PMID 40253526, 2025). "AMPK plays a key role in several cancers by regulating various signaling pathways including mTOR." (PMID 39779613, 2025). "The CuNPs had shown the anti-cytotoxic properties, antioxidant capacity, as well as their ability to suppress PI3K/AKT/mTOR pathway implying that they could be used in the treatment of cancer." (PMID 39787250, 2025). "Moreover, LARP1 has been found to facilitate the onset and metastasis of various cancers via the mTOR pathway." (PMID 39786317, 2025). "Therefore, the MYC/mTOR axis is an attractive therapeutic target in MYC-driven cancers that are addicted to enhanced protein synthesis." (PMID 39779613, 2025). "CSNK2B promotes cell regulation by activating the mTOR signaling pathway in cancers." (PMID 40700255, 2025). "Similarly, mTOR-dependent modulation of mitochondrial dynamics can influence cell transformation and metastasis in cancer." (PMID 40450326, 2025). "Finding out how important it is to target the mTOR pathway and how to use bioactive chemicals from plants to treat cancer are both important discoveries that could lead to more precise medicine and the development of effective cancer drugs." (PMID 40717210, 2025). "Additionally, the complexity of mTOR signaling across different cancer types can impact drug efficacy." (PMID 40299431, 2025).
cancer (continued). "The PI3K/AKT/mTOR signaling pathway is a core regulatory axis in cell growth, proliferation, survival and metabolism, widely involved in the development and progression of various cancers." (PMID 40303931, 2025). "Additionally, much of the research has naturally concentrated on well-established signaling pathways—so-called “usual suspects”—such as PI3K/Akt/mTOR or DNA repair pathways, due to their well-characterized roles in cancer biology." (PMID 40864743, 2025). "CTC-MCC-41 cells showed a high susceptibility for dual targeting of AKT and mTOR in vivo, indicating that selective eradication of CTCs by AKT/mTOR inhibitors may be considered a new treatment option in cancer." (PMID 40129297, 2025). "For example, the combined use of ICIs with targeted therapies that inhibit specific oncogenic pathways, such as the PI3K/AKT/mTOR pathway, could enhance the therapeutic effect by simultaneously targeting the immune system and cancer cells." (PMID 41306967, 2025). "Monotherapy AKT/mTOR inhibitors or combined therapy at reduced doses could offer improved, cost-effective therapy options for gefitinib-resistant cancer." (PMID 40615716, 2025). "Notably, CMG002 exhibits stronger anti-cancer activity at lower concentrations compared to other PI3K/mTOR inhibitors and re-sensitizes chemoresistant cells to paclitaxel or cisplatin." (PMID 40075635, 2025). "By linking the PI3K-Akt-mTOR pathway’s promotion of lipid synthesis to the suppression of ferroptosis, Yi (2020) provided a strong rationale for a new therapeutic strategy: inhibiting this pathway to dismantle cancer cells’ defenses and trigger cell death." (PMID 41210865, 2025). "Certain BCAA metabolites may have inhibitory effects on cancer cells, particularly by modulating the mTOR signaling pathway and other metabolic pathways." (PMID 40438606, 2025). "Hypothesis of this study is that rapamycin, beyond its established role as an mTOR inhibitor, may interact with other oncogenic receptors involved in cancer progression, thereby expanding its potential therapeutic applications." (PMID 39762538, 2025). "Inhibitors targeting PI3K, AKT, and mTOR are undergoing clinical trials for various cancer types." (PMID 40041495, 2025). "Furthermore, NR2F1 bound HSPD1, which can stabilize ATP5A1 in cancer cells, leading to activation of mTOR signaling." (PMID 40955663, 2025). "Therefore, targeting the mTOR has become a promising strategy in cancer therapy, as inhibiting its activity can curb cancer cell proliferation and trigger apoptosis." (PMID 40287470, 2025). "The mTOR signaling pathway is frequently upregulated across various cancer types, promoting uncontrolled tumor cell growth and proliferation, and recently, the importance of mTORC2 for cancer cell metabolic reprogramming, survival, and growth has been acknowledged." (PMID 41429766, 2025). "Many cancers rely on mTOR activity to maintain cellular growth and division." (PMID 41398969, 2025). "Its regulatory roles in the Wnt, PI3K/AKT and mTOR pathways illustrate its importance in maintaining cellular homeostasis and its capability as a therapeutic target in various diseases, including neurodegenerative disorders and cancer." (PMID 41190025, 2025). "Thus, targeting the AKT/mTOR signalling pathway presents a compelling strategy in cancer therapeutics." (PMID 39542458, 2025). "MARK3 may inhibit cancer cell survival through the modulation of PI3K/AKT/mTOR pathway, thereby inhibiting tumor progression." (PMID 40136361, 2025). "Besides, MAPK, PI3K/mTOR and Wnt/β-catenin signaling are also activated in cancer cells in response to the secretion of growth factors and cytokines, both of which promote cancer cell proliferation or EMT transformation." (PMID 40517166, 2025). "Dysregulation of mTOR signaling, including phosphorylation of Ser2448, is common in cancer." (PMID 39941728, 2025).